FAM230B (family with sequence similarity 230 member B)
Synonyms: FLJ46366
Gene: Long non-coding RNA gene on chromosome 22 (21,166,079 to 21,192,161, forward strand). Ensembl gene ENSG00000215498.
Diseases named in the same sentence as FAM230B in open-access papers:
FAM230B is named in the same sentence as 10 diseases in open-access papers, as found by Europe PMC text mining. Sharing a sentence is not in itself a finding about the gene and the disease. The quoted sentences say what the papers report.
gastric cancer (3 papers, 2022 to 2024). A primary or metastatic malignant neoplasm involving the stomach. "According to studies on the etiology of gastric cancer, FAM230B suppresses the transcription of miR-27a-5p, and miR-27a-5p modulates the biological behavior of gastric cancer by diminishing the synthesis of TOP2A27." (PMID 38806610, 2024). "Long non-coding RNA (lncRNA) FAM230B has been reported to participate in gastric cancer and papillary thyroid cancer, while its role in other cancers has not been reported." (PMID 35287554, 2022). "FAM230B is a newly identified lncRNA with known functions only in gastric cancer and papillary thyroid cancer." (PMID 35287554, 2022). "FAM230B was highly upregulated in gastric cancer and it upregulates TOP2A by sponging miR-27a-5p to promote both tumor growth and metastasis." (PMID 35287554, 2022). "The involvement of FAM230B in cancer biology has only been investigated in papillary thyroid cancer and gastric cancer." (PMID 36262247, 2022). "In another study, FAM230B was reported to be upregulated in gastric cancer and promotes tumor metastasis and growth by sponging miR-27a-5p to upregulate TOP2A." (PMID 36262247, 2022). "LncRNA FAM230B participates in gastric cancer and papillary thyroid cancer." (PMID 35287554, 2022).
papillary thyroid cancer (2 papers, 2022). "FAM230B is also highly expressed in papillary thyroid cancer and interacts with the miR-378a-3p/WNT5A axis to accelerate tumor metastasis." (PMID 35287554, 2022). "FAM230B is upregulated in papillary thyroid cancer and increases the expression levels of WNT5A by sponging miR-378a-3p to accelerate tumor metastasis." (PMID 36262247, 2022).
asthma (1 paper, 2022). "Tissue samples (paired LA and non-tumor tissues) from the 60 LA patients and plasma samples from GRD (n = 60), COPD (n = 60), asthma (n = 60), or control (n = 60) were subjected to RNA isolation and RT-qPCR to determine the expression of FAM230B." (PMID 35287554, 2022). "It was observed that increased plasma expression levels of FAM230B effectively separated LA patients from GRD, COPD, asthma, or the control subjects." (PMID 35287554, 2022). "Diagnostic value of FAM230B for LA was evaluated with ROC curve analysis, in which LA patients were true positive cases, and the true negative cases were GRD, COPD, asthma, or control subjects." (PMID 35287554, 2022). "Plasma FAM230B effectively separated LA patients from GRD, COPD, asthma and control groups." (PMID 35287554, 2022). "The expression levels of plasma FAM230B were specifically increased in LA patients, but not in GRD, COPD and asthma patients (p < 0.01)." (PMID 35287554, 2022). "In addition, plasma FAM230B was specifically upregulated in LA patients, but not in GRD, COPD and asthma patients." (PMID 35287554, 2022). "Interestingly, plasma FAM230B is only upregulated in LA, but not in GRD, COPD and asthma patients, compared to that in the controls." (PMID 35287554, 2022).
colorectal cancer (1 paper, 2022). A primary or metastatic malignant neoplasm that affects the colon or rectum. "Long non-coding RNA FAM230B and microRNA (miR-1182) have been characterized as critical players in cancer biology, while their roles in colorectal cancer (CRC) are unclear." (PMID 36262247, 2022).
lung adenocarcinoma (1 paper, 2022). A carcinoma that arises from the lung and is characterized by the presence of malignant glandular epithelial cells. "We then explored the role of FAM230B in lung adenocarcinoma (LA)." (PMID 35287554, 2022).
lung diseases (1 paper, 2022). "Therefore, FAM230B was specifically upregulated in LA, but not other lung diseases." (PMID 35287554, 2022).
tumor (3 papers, 2022 to 2025). "Our study observed the upregulation of FAM230B in LA tissues compared to that in non-tumor tissues, suggesting the oncogenic role of FAM230B in LA." (PMID 35287554, 2022). "FAM230B was highly expressed in LA tissues compared to that in non-tumor samples." (PMID 35287554, 2022). "Although we did not explore the role of FAM230B in the progression of LA, our association analysis showed that plasma expression of FAM230B was only closely correlated with tumor size, but not other factors." (PMID 35287554, 2022). "However, in vivo animal model experiments are needed to validate the role of FAM230B in CRC tumor growth." (PMID 36262247, 2022). "Therefore, FAM230B is likely involved in tumor growth of LA." (PMID 35287554, 2022). "CRC and paired non-tumor tissue samples were collected from 60 CRC patients, and the expression of FAM230B and miR-1182 (premature and mature) in these samples was analyzed with RT-qPCR." (PMID 36262247, 2022). "In conclusion, FAM230B is upregulated in CRC and it suppresses the maturation of miR-1182 to promote tumor growth." (PMID 36262247, 2022). "The expression of FAM230B, premature miR-1182, and mature miR-1182 in CRC and paired non-tumor tissue samples from 64 CRC patients were determined using RT-qPCR." (PMID 36262247, 2022). "The results showed that FAM230B was highly upregulated in LA tissues compared to that in non-tumor samples (p < 0.01)." (PMID 35287554, 2022). "The expression of FAM230B in plasma is only closely correlated with FAM230B in LA tissues, but not FAM230B in non-tumor tissues, suggesting that plasma FAM230B in LA patients is mainly from LA tissues." (PMID 35287554, 2022). "It showed that plasma FAM230B was closely correlated with tumor size, but not other clinical factors of LA patients." (PMID 35287554, 2022). "Plasma FAM230B was closely correlated with tumor size, but not other clinical factors of LA patients." (PMID 35287554, 2022). "However, plasma expression of FAM230B was not closely correlated with FAM230B in non-tumor tissues." (PMID 35287554, 2022). "Therefore, FAM230B was likely involved in tumor growth, but not other aspects of LA." (PMID 35287554, 2022).
cancer (2 papers, 2022). A tumor composed of atypical neoplastic, often pleomorphic cells that invade other tissues. "In both cancers, FAM230B can sponge miRNAs to upregulate the expression of downstream oncogenes to promote cancer progression." (PMID 35287554, 2022). "lncRNA FAM230B and miR-1182 have been characterized as critical players in cancer biology, while their role in CRC is unclear." (PMID 36262247, 2022).
FAM230B also shares sentences with these, for which no sentence is quoted: Hypertension (1 paper); thyroid cancer (1).